TMIGD2 (transmembrane and immunoglobulin domain containing 2)
Description:
Plays a role in cell-cell interaction, cell migration, and angiogenesis. Through interaction with HHLA2, costimulates T-cells in the context of TCR-mediated activation. Enhances T-cell proliferation and cytokine production via an AKT-dependent signaling cascade.
Synonyms: IGPR-1; CD28H; IGPR1; MGC23244
Tractability: Antibody: UniProt places it where antibodies can reach, with high confidence; UniProt predicts a signal peptide or a membrane-spanning region; its Gene Ontology location is reachable by antibodies, with medium confidence.
Gene: Protein-coding gene on chromosome 19 (4,292,227 to 4,302,431, reverse strand). Ensembl gene ENSG00000167664.
Subcellular location: Cell membrane
Gene Ontology:
Molecular function: coreceptor activity; protein binding
Biological process: positive regulation of activated T cell proliferation; positive regulation of angiogenesis; positive regulation of cytokine production; T cell costimulation
Cellular component: neuron projection; plasma membrane
Genetic constraint (gnomAD): Loss-of-function variants: 19 observed, 20.76 expected, observed/expected ratio (o/e) 0.92, 90% interval 0.64 to 1.34. The upper end of that interval is the gene's LOEUF score, 1.34, which puts it in group 5 of 6, group 1 being the genes least tolerant of losing a copy. Missense variants: 361 observed, 376.07 expected, observed/expected ratio (o/e) 0.96, 90% interval 0.88 to 1.05. Synonymous variants: 184 observed, 154.47 expected, observed/expected ratio (o/e) 1.19, 90% interval 1.06 to 1.35.
Homologues: Orthologues: chimpanzee TMIGD2 (97% identical), macaque TMIGD2 (85% identical), pig TMIGD2 (56% identical).
Diseases named in the same sentence as TMIGD2 in open-access papers:
TMIGD2 is named in the same sentence as 47 diseases in open-access papers, as found by Europe PMC text mining. Sharing a sentence is not in itself a finding about the gene and the disease. The quoted sentences say what the papers report.
colorectal cancer (5 papers, 2017 to 2025). A primary or metastatic malignant neoplasm that affects the colon or rectum. "TMIGD2 has been shown to facilitate multicellular aggregation in colorectal cancer, with disruption of its adhesion function impairing both multicellular aggregation and tumor growth." (PMID 39789663, 2025). "Further research may verify the therapeutic values of the HHLA2-KIR3DL3/TMIGD2 pathway in colorectal cancer." (PMID 36982953, 2023). "Therefore, manipulating the HHLA2-KIR3DL3/TMIGD2 pathway may contribute to the promising strategy of colorectal cancer treatment." (PMID 36982953, 2023). "The different interaction between TMIGD2 and B7-H5 have been identified in certain cancers, such as lung cancer, osteosarcoma, oral squamous cell carcinoma (OSCC), colorectal cancer (CRC) and glioma." (PMID 35193632, 2022). "We revealed the role of HHLA2 expression as a stimulatory and inhibitory immune checkpoint in colorectal cancer, highlighting that the HHLA2–KIR3DL3/TMIGD2 pathway may contribute to the promising strategy of colorectal cancer treatment." (PMID 36982953, 2023).
glioma (4 papers, 2022 to 2025). A benign or malignant brain and spinal cord tumor that arises from glial cells (astrocytes, oligodendrocytes, ependymal cells). "Collectively, these findings indicate that the TMIGD2 molecule is associated with less aggressive clinicopathological characteristics in glioma patients." (PMID 37261362, 2023). "After characterizing the expression pattern of TMIGD2 according to clinical parameters in gliomas, we next investigated the association between TMIGD2 and angiogenesis markers." (PMID 37261362, 2023). "On the other hand, Mantel-Cox analysis demonstrated that increased expression of TMIGD2 in human gliomas is associated with good overall survival." (PMID 37261362, 2023). "To assess the association between TMIGD2 gene expression and clinical features of glioma patients, we analyzed transcriptomic data from the TCGA (248 grade 2, 264 grade 3, and 153 grade 4 patients) and the CGGA cohorts (188 grade 2, 255 grade 3, and 249 grade 4 patients)." (PMID 37261362, 2023). "Overall, TMIGD2 could be a potential therapeutic target associated with improved OS in glioma patients." (PMID 37261362, 2023). "Regarding the OS analysis, our findings indicated that glioma patients with high TMIGD2 expression presented an improved outcome." (PMID 37261362, 2023). "Taken together, our results highlight the tight implication of TMIGD2 in glioma progression and show its promising therapeutic potential as a stimulatory target for immunotherapy." (PMID 37261362, 2023). "Considering that TMIGD2 belongs to the B7 family, our study is the first to examine the association of TMIGD2 expression with PD-L1, B7H3, and B7H6 in gliomas." (PMID 37261362, 2023). "Cox multivariable analysis revealed that TMIGD2 is an independent predictor of a good prognosis in glioma patients." (PMID 37261362, 2023). "As compared to grade 2 and grade 3 gliomas, glioblastomas expressed a lower level of TMIGD2 transcript (p= 0.0006; p= 0.0038)." (PMID 37261362, 2023). "Our current data shows for the first time that a high TMIGD2 expression profile displays a favorable outcome in patients with gliomas." (PMID 37261362, 2023). "In the present study, we first assessed TMIGD2 mRNA expression using the Cancer Genome Atlas (TCGA) glioma transcriptome dataset (667 patients), followed by validation with the Chinese Glioma Genome Atlas (CGGA) cohort (693 patients)." (PMID 37261362, 2023). "We, hence propose combining anti-VEGF treatment and selective activation on naive T cells in patients with high TMIGD2 to enhance anti-tumor response and prognosis in glioma patients." (PMID 37261362, 2023). "TMIGD2 expression was found to be significantly higher in astrocytoma, IDH-1 mutations, low-grade, and young glioma patients." (PMID 37261362, 2023). "Secondly, we examined TMIGD2 protein staining in a series of 25 paraffin-embedded blocks from Moroccan glioma patients." (PMID 37261362, 2023). "In the present study, we assessed TMIGD2 expression levels in glioma patients, demonstrating its potential use as a target for immunotherapy." (PMID 37261362, 2023). "TMIGD2 expression has been found to be significantly upregulated in glioma patients, correlating with better overall survival and increased immune cell infiltration, and is negatively associated with pathways such as angiogenesis and hypoxia, suggesting its role in inhibiting tumor progression." (PMID 40255615, 2025). "This study is the first to characterize TMIGD2 expression on human glioma cells." (PMID 37261362, 2023). "Our results suggest that high TMIGD2 expression may be involved in the anti-tumor immune response and in the inhibition of glioma development." (PMID 37261362, 2023). "In addition, infiltration of B cells, CD4 T cells, NKTs, Tr1s, nTregs, iTregs, Th1s, Th17s, Tfhs, and Tcms was reduced in gliomas with high TMIGD2 levels." (PMID 37261362, 2023).
glioma (continued). "Interestingly, we observed a significantly lower expression of genes such as PDGFA, FGFR1, DLL4, and VEGFA in glioma patients with a higher TMIGD2 profile." (PMID 37261362, 2023). "Our findings suggest that overexpression of TMIGD2 may promote infiltration of antitumor immune cell subsets in the glioma TME." (PMID 37261362, 2023). "The expression profile of TMIGD2 and its significance in the overall survival of glioma patients remains unknown." (PMID 37261362, 2023). "More importantly, TMIGD2 may be a relevant biomarker for patient selection and for response to immunotherapy evaluation in gliomas." (PMID 37261362, 2023). "TMIGD2 was expressed on immune cells and, surprisingly, on tumor cells of glioma patients." (PMID 37261362, 2023). "Additionally, TMIGD2 represents an independent predictor of a good prognosis in glioma patients." (PMID 37261362, 2023). "However, the expression profile of the TMIGD2 immune checkpoint and its prognostic value in gliomas remain unknown." (PMID 37261362, 2023). "Besides, some studies targeting NK cells have shown that they are more abundant in low-grade gliomas than in high-grade gliomas.Given that TMIGD2 is constitutively expressed on naive T cells and most NK cells, this may explain the low level of TMIGD2 in HGG tissue." (PMID 37261362, 2023). "Conversely, in gliomas and pancreatic ductal adenocarcinomas, tumors with high levels of HHLA2 expression had a better prognosis, suggesting that it may act as a co-stimulator through the TMIGD2 pathway." (PMID 37261362, 2023).
oral squamous cell carcinoma (4 papers, 2019 to 2023). "In dysplasia and oral squamous cell carcinoma, elevated levels of both HHLA and TMIGD2 also demonstrated a poor prognosis." (PMID 37261362, 2023). "In this study, we used oral squamous cells carcinoma (OSCC) tissue microarrays and immunohistochemistry methods to investigate the expression patterns of HHLA2 and TMIGD2 in OSCC." (PMID 31089395, 2019).
ovarian carcinoma (4 papers, 2021 to 2025). A malignant neoplasm originating from the surface ovarian epithelium. "Growing evidence supports its clinical relevance across malignancies: microRNA-486-3p-mediated regulation of TMIGD2 influences cisplatin resistance in ovarian cancer, while miR-615-5p exerts antitumor effects in cervical cancer via TMIGD2 targeting." (PMID 41208974, 2025). "Furthermore, emerging studies have indicated that TMIGD2 plays a significant role in stimulating the proliferation and migration of ovarian cancer cells." (PMID 39789663, 2025). "MSLN was positively correlated with immunosuppressive genes in ovarian cancer, such as LGALS9, CD276, TMIGD2, CD200, TNFRSF14, and human leukocyte antigen (HLA)-related families including HLA-DRA, HLA-DRB1, HLA-DPA1, HLA-DMA, HLA-E, etc.." (PMID 35692779, 2022). "Thus, the receptors that can interact with HHLA2 expressed in ovarian cancer cells may not be TMIGD2." (PMID 33962626, 2021).
colon cancer (3 papers, 2017 to 2025). "In contrast, CD27, CD276, LAG3, LGALS9, PDCD1, and TMIGD2 showed a highly enriched trend of expression with RFX1 in colon cancer." (PMID 41425715, 2025).
gastric cancer (3 papers, 2018 to 2023). A primary or metastatic malignant neoplasm involving the stomach. "In gastric cancer, elevated TMIGD2 expression predicts a bad prognosis, mainly when its ligand HHLA2 is strongly co-expressed." (PMID 37261362, 2023). "Accordingly, HHLA2 may exert a costimulatory effect against the T cell-mediated immune response via TMIGD2 in patients with gastric cancer." (PMID 29774123, 2018). "Contrary to these results, patients with negative HHLA2/TMIGD2 expression presented a significantly higher 5-year OS compared to the positive groups of gastric cancer." (PMID 37261362, 2023). "In gastric cancer, immunohistochemistry analysis reported that TMIGD2 protein was expressed in GC and noncancerous samples, and on immune cells in both tissues." (PMID 37261362, 2023).
acute myeloid leukemia (2 papers, 2024 to 2025). Acute myeloid leukemia (AML) is a group of neoplasms arising from precursor cells committed to the myeloid cell-line differentiation. "Recent research has also revealed aberrant expression of TMIGD2 in acute myeloid leukemia cells, underscoring its critical role in disease progression." (PMID 39789663, 2025).
dysplasia (2 papers, 2019 to 2023). A usually neoplastic transformation of the cell, associated with altered architectural tissue patterns. "After comparing the HHLA2 and TMIGD2 expression levels in OSCC, dysplasia, and mucosa, we found increased HHLA2 expression in OSCC and dysplasia, while the TMIGD2 expression was decreased in OSCC and dysplasia." (PMID 31089395, 2019).
astrocytomas (1 paper, 2023). "In addition, high TMIGD2 protein staining on immune cells was significantly associated with the astrocytoma subtype." (PMID 37261362, 2023). "On tumor cells, however, TMIGD2 is more highly expressed on ependymoma and astrocytoma subtypes than on glioblastoma (p= 0.0417; p= 0.0035)." (PMID 37261362, 2023). "Besides, TMIGD2 expression was upregulated in the astrocytoma subtype compared to glioblastoma (p< 0.0001)." (PMID 37261362, 2023). "Moreover, our results showed that astrocytomas are enriched with immune cells expressing high levels of TMIGD2, unlike oligodendrogliomas and glioblastomas subtypes (p= 0.0091; p= 0.0006)." (PMID 37261362, 2023).
chordoma (1 paper, 2021). Chordomas are rare malignant tumors arising from embryonic remnants of the notochord in axial skeleton. "Altogether, whether HHLA2 affects chordoma biology and patient outcome through TMIGD2 signaling or other molecular pathways to inhibit antitumor immune responses deserves further confirmation." (PMID 35145510, 2021).
endometrial cancer (1 paper, 2025). Primary or metastatic malignant neoplasm involving the endometrium (mucous membrane that lines the endometrial cavity). "Given its involvement in multiple malignancies, including endometrial cancer and small cell lung cancer, TMIGD2 is increasingly recognized as a promising therapeutic target across various cancers." (PMID 39789663, 2025).
ependymoma (1 paper, 2023). A WHO grade II, slow growing tumor of children and young adults, usually located intraventricularly. "In contrast to tumor cells, TMIGD2 protein staining was strongly associated with ependymoma subtype." (PMID 37261362, 2023).
glioblastoma (1 paper, 2023). The most malignant astrocytic tumor (WHO grade IV). "In the TCGA group, oligoastrocytomas and oligodendrogliomas displayed a high level of TMIGD2 than the glioblastomas subtype (p= 0.0010; p= 0.0010)." (PMID 37261362, 2023).
Leukaemia (1 paper, 2024). "Here, the authors show that TMIGD2 is expressed in Acute Myeloid Leukaemia stem cells regulating self-renewal and differentiation to facilitate leukemogenesis." (PMID 38167704, 2024). "Among the genes with significant changes upon TMIGD2 depletion were factors closely associated with cell-cycle (CDKN1A and CCND1) and leukemia stemness (CD93 and IL1RAP)." (PMID 38167704, 2024). "We also demonstrated that knockdown of TMIGD2 using shRNA or targeting TMIGD2 with mAbs significantly decreased colony-forming capacity of LSCs and effectively reduced leukemia burden in PDX models, highlighting TMIGD2 as a novel therapeutic target for AML treatment." (PMID 38167704, 2024). "Targeting TMIGD2 signaling with anti-TMIGD2 monoclonal antibodies attenuates LSC self-renewal and reduces leukemia burden in AML patient-derived xenograft models but has negligible effect on normal hematopoietic stem/progenitor cells." (PMID 38167704, 2024). "To further evaluate the functions of TMIGD2 and HHLA2 in leukemia cells, we next performed small hairpin RNA (shRNA)-mediated knockdown of TMIGD2 (shTMIGD2) or HHLA2 (shHHLA2) in Kasumi-1, HEL and K562 cell lines." (PMID 38167704, 2024). "We observed significant reduced leukemia burden in both rounds of PDX mice, indicating that anti-TMIGD2 mAb preferentially inhibit leukemogenesis by targeting TMIGD2-expressing LSCs." (PMID 38167704, 2024). "Loss of TMIGD2, but not HHLA2, led to significant inhibition of leukemia cell growth over the course of 6 days." (PMID 38167704, 2024). "20F2 opsonized primary leukemia cells resulted in a significantly higher ADCP activity compared with control mIgG2a, suggesting that 20F2 may both block oncogenic TMIGD2 signaling and induce ADCP." (PMID 38167704, 2024).
lymph node metastasis (1 paper, 2025). "Moreover, a notable association was established between TMIGD2 mRNA levels and both lymph node metastasis (P = 0.009) and FIGO stage (P = 0.010)." (PMID 39789663, 2025).
multiple myeloma (1 paper, 2025). "It has been reported that CD200, TMIGD2 and TNFSF14 can facilitate anti-tumor immune responses by enhancing T and NK cell activity in multiple myeloma and hematologic malignancies." (PMID 40342824, 2025).
T-cell acute lymphoblastic leukemia (1 paper, 2024). Acute lymphoblastic leukemia of T-cell origin. "TMIGD2 mRNA was highly expressed in AML and T-cell acute lymphoblastic leukemia cell lines, whereas no other tumor types exhibited substantial TMIGD2 expression." (PMID 38167704, 2024).
tumor (30 papers, 2017 to 2025). "As part of our study, we assessed the association between TMIGD2 expression and various genes associated with angiogenesis and tumor progression." (PMID 37261362, 2023). "Overall, our study suggests that TMIGD2 expression was positively associated with anti-tumor immune cell infiltration, while negatively associated with pro-tumor immune cell subsets." (PMID 37261362, 2023). "Accordingly, our results suggest that high TMIGD2 expression may be associated with low angiogenesis potential and thus with a lower risk of tumor development and metastasis." (PMID 37261362, 2023). "miR-615-5p exerted its tumor-suppressive effects by inhibiting cell growth and metastasis through the regulation of TMIGD2." (PMID 39789663, 2025). "In this study, we found that the mRNA expression levels of IDO1 were higher than those of TMIGD2 in nearly all patients, indicating that both the activation of inhibitory immune pathways and the weakening of stimulatory pathways promote tumor immune evasion." (PMID 40061889, 2025). "A recent study using B7H7+ tumor cells showed that TMIGD2 is an activator of NK cells and demonstrated its promising potential as a target to enhance anti-tumor activity." (PMID 37261362, 2023). "The angiogenic phenotype of endothelial cells in culture was considerably influenced by the ectopic expression or silencing of TMIGD2 expression, and the introduction of TMIGD2 to tumor cells promoted tumor angiogenesis via the SPIN90/WISH signaling axis." (PMID 37261362, 2023). "TMIGD2 protein staining results showed an upregulation on both tumor and immune cells in LGG versus HGG patients." (PMID 37261362, 2023). "TMIGD2 was mainly expressed in tissue-resident lymphocyte T cells, related to improved tumor prognosis." (PMID 35193632, 2022). "The restricted expression pattern of TMIGD2 weakens the stimulatory immune pathways, contributing to tumor immune evasion, which may explain the relatively low TMIGD2 expression levels observed in BRCA." (PMID 40061889, 2025). "Moreover, depletion of TMIGD2 also significantly arrested tumor growth in HEL and K562 subcutaneous xenograft models of AML in NSG mice." (PMID 38167704, 2024). "Otherwise, therapies targeting TMIGD2 may not only improve antitumor immune responses, but also affect tumor angiogenesis.In recent years, exciting progress has been made in the use of ICI in several solid tumors." (PMID 37261362, 2023). "Interestingly, TMIGD2 protein expression was upregulated on infiltrating immune cells and tumor cells in LGG patients (p= 0.0012; p= 0.0029)." (PMID 37261362, 2023). "Nevertheless, HHLA2 expression on tumor cells has also been reported to stimulate tumor angiogenesis through interactions with TMIGD2 on the endothelium, which may result in a poor prognosis." (PMID 32509772, 2020). "Further analysis of immune-stimulating factors revealed that in tumors such as LGG, PRAD, and BRCA, the expression of PLAG1 was significantly positively correlated with immune-stimulating factors like CD48, CD27, and TMIGD2, which may enhance anti-tumor immune responses." (PMID 40276502, 2025). "Many downregulated genes in tumour‐infiltrating peripheral CD8+ T cells are associated with classical IFN responses (IFI6, IFI27, MX1, STAT1, EPSTI1 PARP9, ISG15), cell proliferation (STMN1, CENPF, HELLS, NUSAP1, and DNPH1), and T cell costimulation (CD28, TMIGD2, TNFRSF4, CD27, and TNFRSF18)." (PMID 39350478, 2024). "Along with previous findings, in ICC, HHLA2 may not only work as an inhibitory checkpoint, but also potentially contribute to tumor progression through binding to TMIGD2, a recently identified ligand which is also involved in angiogenesis, or through other unknown mechanisms." (PMID 30885276, 2019). "In our study, the expression levels of HHLA2 and TMIGD2 in different OSCC pathology grades, tumor sizes, and lymph node status were analyzed by the one-way analysis of variance method and t-test method." (PMID 31089395, 2019).